IL2 (interleukin 2)
Diseases named in the same sentence as IL2 in open-access papers (continued):
Sharing a sentence is not in itself a finding about the gene and the disease.
liver disease (12 papers, 2012 to 2025). "From the perspective of liver disease such as non-alcoholic steatohepatitis, the inflammatory cytokines (IL-1β, IL-2, and TNF-α) are produced in the liver and are associated with disease (Bruscalupi, Agostinelli, Stronati & Cucchiara, 2015)." (PMID 34917853, 2021). "CD25 is the high affinity receptor for IL-2, a cytokine overexpressed in inflammatory liver diseases, and showed a clear and almost exclusive expression on liver-resident CD49a+ NK cells." (PMID 28792982, 2017). "In liver diseases, the production of IL-2 is increased in liver tissues as well as in serum (soluble IL-2), and is considered a biomarker for poor prognosis." (PMID 28792982, 2017). "Altogether, we demonstrate that liver-resident CD49a+ NK cells in humans with advanced liver disease include subsets of CD25+ proliferating cells responding to low doses of exogenous IL-2 as well as NK cell subsets expressing CXCR3, the receptor for IP-10, and CD34, a marker for progenitor NK cells." (PMID 28792982, 2017). "Therefore, IL‐2 therapy may successfully restore intrahepatic Treg numbers and function in liver disease." (PMID 26928938, 2016). "Many studies have suggested that various cytokines, such as IL-2, IL-6, IL-8, IL-10, and IL-12 were involved in the progression of HBV-related liver disease and HCC." (PMID 31200663, 2019). "In the context of liver diseases, cytokines have been assigned fundamental properties reflecting common function, including proinflammatory cytokines (e.g. IL‐1α, IL‐1β, TNF‐α, and IL‐2), immunoregulatory cytokines (e.g. IFN-γ), and anti-inflammatory cytokines (e.g. IL-10 and IL-4)." (PMID 33841403, 2021). "Administration of Interleukin-2 (IL-2), a cytokine that has been demonstrated to control the development of CD4+ T cell subsets including Tregs, is an example of this strategy and has been investigated in both liver disease and transplantation." (PMID 34721383, 2021). "The effect of liver disease on gene expression was confirmed in multivariable models after adjustment for potential confounders (age, sex, BMI): all the inflammasome components (P2X7R, P2X4R, NLRP3, CASP1, AIM2, IL-2) were significantly related to the liver disease (0.0007 < p <0.037)." (PMID 35806450, 2022). "Thus, it is anticipated that Treg therapy for liver diseases would benefit from adjuvant supply of low-dose IL-2, which can selectively potentiate Treg function without establishing global immune activation." (PMID 27656181, 2016).
lung adenocarcinoma (12 papers, 2015 to 2025). A carcinoma that arises from the lung and is characterized by the presence of malignant glandular epithelial cells. "For Instance, the E2 enzyme UBE2T inhibited CD8+ T-cell infiltration and expression of immune-promoting factors (IFN-γ, TNF-α and IL-2) in lung adenocarcinoma by activating the glycolytic pathway upon binding to FOXA1." (PMID 40183093, 2025). "In lung adenocarcinoma patients, compared with smoking subjects, the concentrations of IL-2, IL-4, IL-6, and IL-10 were increased." (PMID 26582240, 2015). "Our results showed higher levels of proinflammatory (IL-2 and IL-6) and anti-inflammatory (IL-4 and IL-10) cytokines in lung adenocarcinoma patients compared with smoking subjects." (PMID 26582240, 2015). "Higher levels of IL-2 could also relate to increased activity of CD8+ T cells in female lung adenocarcinoma patients." (PMID 33526761, 2021). "In addition, lung adenocarcinoma patients increased both plasma concentrations of IL-2, IL-4, IL-6, and IL-10, and proportions of Latency Associated Peptide (LAP) TGF-β subset of CD4+CD25+CD127− Treg cells, which overexpressed LAP TGF-β." (PMID 26582240, 2015). "CircMET binds to the RBP YBX1 in lung adenocarcinoma, blocking YBX1’s interaction with IL-2 mRNA and suppressing IL-2 translation, which further illustrates how circRNA-RBP interactions disrupt cytokine production and T cell activation." (PMID 41425089, 2025). "Utilizing IL-2 successfully counteracts the inhibitory impact of elevated IRF1 expression on the proliferation, migration, and invasion of lung adenocarcinoma cells." (PMID 38915471, 2024). "Subsequently, it is verified that 9 core targets for ginseng treatment of lung adenocarcinoma, namely, JUN, IL-1β, IL-2, ICAM1, HMOX1, MMP9, MMP2, PTGS2, and TNF, are closely related to the proliferation, migration, and apoptosis of lung adenocarcinoma cells." (PMID 32802118, 2020). "Meanwhile, according to the results of qRT-PCR, it is speculated that ginseng can treat lung adenocarcinoma by up-regulated JUN, IL-1β, IL-2, ICAM1, HMOX1, MMP9, and MMP2 targets and down-regulated PTGS2 and TNF genes." (PMID 32802118, 2020). "We mixed lung adenocarcinoma, A549 cells (5×103) per well together with different ratios of NK cells (NK cells: A549 cells=0.5:1, 1:1, 2:1, 4:1) in 96-well plate either in the presence or absence of 100U/mL of IL-2 for 24 h." (PMID 26516316, 2015).
malignant glioma (12 papers, 2000 to 2023). A grade III or grade IV glioma arising from the central nervous system. "Cytokines such as IL-2 and IL-15 are beginning to find a role in the management of patients with malignant gliomas." (PMID 38002466, 2023). "Conventionally, adoptive immunotherapy using lymphokine-activated killer cells, which are patient-derived high-dose IL-2-stimulated PBMCs, presented the possibility of a new treatment for patients with malignant glioma, including GBM." (PMID 37563692, 2023). "A clinical trial in patients with recurrent malignant glioma using autologous IL-2-activated-NK cells as monotherapy was safe but only partially effective, possibly due to local immunosuppression and MHC I expression." (PMID 23762498, 2013). "Whether PEG-IL-10 alone or in combination with IL-2 holds promise for treating malignant gliomas remains to be seen." (PMID 26217588, 2015). "IL-2, for example, appears to potentiate the anti-tumor response in malignant gliomas." (PMID 26217588, 2015). "Moreover, IL-2 related toxicities that emerged in some studies such as brain edema and aseptic meningitis have disturbed widespread use of this strategy for malignant gliomas." (PMID 25009822, 2014). "In a pilot study exclusively performed to date against patients with recurrent malignant gliomas that were treated with intratumoral infusion of ex vivo expanded autologous TILs with IL-2, one of six patients showed complete remission, two had partial responses, and three died of tumor progression." (PMID 25009822, 2014). "The results indicate that the novel combination of IL-2 and histamine can be of value in reducing intracerebral tumour growth and, thus, it might be of interest to re-evaluate the therapeutic potential of biotherapy in malignant glioma." (PMID 10952789, 2000).
pertussis (12 papers, 2011 to 2023). A contagious bacterial respiratory infection caused by Bordetella pertussis. "The acellular pertussis vaccines induced a mixed cytokine profile showed elevated IFN-γ production (associated with IL-2), low IL-4, and more abundant IL-5 production." (PMID 37574522, 2023). "For pertussis with compromised seroprotective titers in all the study groups, a significant association with gestation age, monocyte, and plasma levels of IL-6, IL-10, and IL-2 was found in univariate analysis, but plasma IL-6 levels emerged to be the significant parameter in multivariate analysis." (PMID 33968011, 2021). "The whole-cell pertussis vaccinations were characterized by an elevated production of T-helper cell type 1 cytokines, such as IFNγ or IL-2." (PMID 37574522, 2023). "Here, we have used responses to individual components of the DTP vaccine [tetanus toxoid (TT), diphtheria toxoid (DT), whole cell inactivated pertussis] to characterize the NK cell subsets involved in interleukin-2-dependent recall responses." (PMID 24843874, 2014). "In CB samples, plasma IL-2, IL-17A, IL-31, sCD14, and switched memory B cells were positively associated, whereas APRIL, IL-33, non-switched memory B cells, and plasmablasts were negatively associated with 12-month pertussis IgG levels." (PMID 37251388, 2023). "Using a least absolute shrinkage and selection operator (lasso) regression model, cord blood (CB) plasma IL-2, IL-17A, IL-31, and soluble CD14 (sCD14) were positively associated with pertussis IgG levels at 12 months, while CB plasma concentrations of APRIL and IL-33 were negatively associated." (PMID 37251388, 2023). "IL-2 acts as a T cell growth factor and its elevation in infants at seven weeks of age may enhance the expansion and activation of T cells that are primed by subsequent primary pertussis immunisation." (PMID 34649076, 2021). "Regarding cellular immunity, 15 days after vaccination, frequency of pertussis-specific CD4+ T cells, quantified by staining for IFN-γ, IL-2 and TNF-α, was equivalent in both groups supporting the induction of T cell immunity." (PMID 37468500, 2023). "Loss of NK cell cytotoxicity to pertussis vaccination has previously been demonstrated to correlate with increased frequency of CD57+ NK cells; thus, expansion of the CD57+ NK cell population in CMV-seropositive donors may affect total NK cell activation to IL-2 secretion." (PMID 35192547, 2022). "Other authors have demonstrated that a transgenic mouse that expressed CCL2 under the GFAP promoter developed pertussis-induced reversible inflammatory encephalopathy and that CCL2 directed a Th1-biased inflammatory reaction, as shown by high levels of TNF-α, INFγ and IL-2 in the CNS." (PMID 23866683, 2013). "This may indicate that pertussis induces some IL-12 and IL-18 (such that LCC is redundant in these assays), whereas H1N1 may be a poor inducer of IL-12 and IL-18 but a better inducer of IL-2 or other accessory cytokines." (PMID 25855356, 2015). "As observed with pertussis, statistically significant induction of CD25, CD25/IFN-γ, and CD107a was observed in response to restimulation with H1N1 Ag, and IL-2 blocking significantly decreased CD25/IFN-γ expression, whereas IgG depletion inhibited the degranulation (CD107a) response." (PMID 25855356, 2015).
Pleural effusion (12 papers, 1996 to 2021). The presence of an excessive amount of fluid in the pleural cavity. "This study aimed to retrospectively present our experience in treating pediatric cancer patients with pleural effusion, ascites, and pericardial effusion using interleukin-2 (IL-2) and dexamethasone (DEX) intracavitary injections." (PMID 34872514, 2021). "This retrospective study illustrates that thoracic, intraperitoneal, or pericardial intracavitary injection of DEX plus IL-2 can be an effective and safe treatment for pediatric cancers with pleural effusion, ascites, and pericardial effusion." (PMID 34872514, 2021). "The concentration of cytokines (IL-6, TNFα, IFNɤ, MCP-1, IL-2) in pleural effusion were higher in mice in the BCG + SiCon group than in the PBS + SiCon group, which is consistent with previous studies." (PMID 30669315, 2019). "In our study the IL-2 levels in the pleural effusion of patients with tuberculous pleurisy and tuberculous empyema had no statistical difference, as well as the two groups of tuberculous empyema." (PMID 27034588, 2016). "The concentration of IL-2, IL-12, IL-18 and IL-23 in supernatants from Mtb-stimulated blood PBMCs and cells from pleural effusions of TB patients were measured by Luminex method." (PMID 27586092, 2016). "The previous reports had stated that the IL-2 levels in pleural effusions of cancer and empyema patients were lower than tuberculous pleurisy patients." (PMID 27034588, 2016). "Combinations of other stimuli such as IL-2 plus IL-7, IL-2 plus IL-12, or IL-2 plus TCR-CD3 engagement also reverse the immunosuppressed state of pleural effusion T-cells; remarkably, cytolysis of autologous tumor cells is mainly mediated by CD8+ T-cells." (PMID 23118782, 2012). "Several studies suggested that recombinant IL-2 may be effective for pleural effusion due to the ability to activate lymphokine-activated killer cells, which could induce a cytologic response to malignant pleurisy." (PMID 34872514, 2021). "We also assessed whether NK cells from pleural effusion of tumors of different origin were able to respond to IL-2 short-time treatment, both when directly isolated from PE fluids or when polarized with PE fluids in vitro." (PMID 29713652, 2018). "We investigated whether NK cells from peripheral blood (PB) and pleural effusions of patients develop decidual-like NK phenotype and whether exposure to IL-2 can restore their killing ability in the presence of pleural fluids." (PMID 29713652, 2018). "IL-2 levels in pleural effusions due to various diseases had been reported." (PMID 27034588, 2016). "Moreover, we found strong positive correlations between Th1 cytokines (IFN-γ, IL-12p70 and IL-2) and sAPRIL in the pleural effusion of TP patients." (PMID 22719887, 2012). "Anecdotal evidence has suggested that lymphokine-activated killer cells and IL-2 might reduce the formation of pleural effusions, and an early trial with IL-2 suggested survival benefit, with a subsequent phase II trial reporting tumour responses in 22% of patients with malignant mesothelioma." (PMID 34226685, 2021). "Higher expression of IL-2 mRNA was connected with crept, wheezing and chest X-ray findings like central perihilar infiltrate, patchy infiltrate, consolidation, hilar lymphadenopathy, pneumothorax, pleural effusion which showed higher expression compared to counterpart (p< 0.0001)." (PMID 33413198, 2021). "The IL-2, IL-12, and IL-18 production was higher in supernatants of cells from pleural effusions than blood PBMCs, while IL-23 production was lower in supernatants of cells from pleural effusions; however, only the difference in IL-2 production was statistically significant." (PMID 27586092, 2016). "The possible mechanism of IL-2 in treating adult pleural effusion is that IL-2 increases the numbers of CD3 + T cells and NK cells in the pleural space and enhances the immune response, thus reducing the incidence of pleural effusion." (PMID 34872514, 2021).
Pleural effusion (continued). "Among patients who received IL-2 and DEX Injection, 58 patients only had pleural effusion (including bilateral pleural effusions in 29 patients), while 15 only had ascites." (PMID 34872514, 2021). "There are few reports about the IL-2, IL-6, and TNF-α levels in pleural effusions of patients with tuberculous pleurisy and tuberculous empyema." (PMID 27034588, 2016). "Thus, we examined the levels of Th1 cytokines (IFN-γ, IL-12p70 and IL-2) in plasma (HD, n = 15; LTBL, n = 11; LTBH, n = 14; TB, n = 11) and pleural effusion from TP patients (n = 10) by Luminex platform." (PMID 22719887, 2012). "Furthermore, NK cells in pleural effusion from MPM patients are functional and produce high amounts of TNF-α and INF-γ upon stimulation but have also an impaired expression of perforin, which can be restored by IL-2 stimulation in vitro." (PMID 34249695, 2021). "Initially, we administered IL-2 and DEX without obtaining a pathological diagnosis to save the patient’s life when imaging examination revealed a potentially malignant tumor associated with pleural effusion, ascites, or pericardial effusion, especially in critically ill children." (PMID 34872514, 2021). "We aimed to examine whether the interleukin-1β (IL-1β), IL-2, IL-6, tumor necrosis factor-α (TNF-α), plasminogen activator inhibitor type-1 (PAI-1), and tissue plasminogen activator (t-PA) levels were different in pleural effusions of tuberculous pleurisy and tuberculous empyema." (PMID 27034588, 2016). "The aim is to examine whether the interleukin-1β (IL-1β), IL-2, IL-6, tumor necrosis factor-α (TNF-α), plasminogen activator inhibitor type-1 (PAI-1), and tissue plasminogen activator (t-PA) levels were different in pleural effusions of tuberculous pleurisy and tuberculous empyema." (PMID 27034588, 2016).
Splenomegaly (12 papers, 2014 to 2026). Abnormal increased size of the spleen. "In line with other reports, treatment with IL-2 complexes caused severe splenomegaly and lymphadenopathy in otherwise naïve mice, with the total number of splenocytes increasing by 120 million cells on average (i.e. two-fold)." (PMID 26731275, 2016). "Mice pretreated with S4B6/IL-2 complexes had increased splenomegaly as well as significantly higher numbers of donor CD4+ T cells with a central memory phenotype." (PMID 29670626, 2018). "Nevertheless, given the absolute cell numbers of Treg expansion, the massive splenomegaly and lymphadenopathy observed in mice treated with IL-2 complexes cannot be solely explained by the expansion of Tregs." (PMID 26731275, 2016). "Investigations may reveal splenomegaly, cytopenia, hypertriglyceridemia, hemophagocytosis, low/absent natural killer (NK) cell activity, raised ferritin, or elevated interleukin 2 levels." (PMID 31230590, 2019). "Also, due to impaired hematopoiesis splenomegaly was observed at 11 weeks after cell transfer in all Il2−/− recipients." (PMID 28415569, 2017). "There was increased splenomegaly with RD2 by infiltration of cytotoxic CD8+ T cells expressing Perforin and Granzyme B. These alloimmune T cells showed a pro-inflammatory IL-2 and IFN-γ expression profile as well." (PMID 34177940, 2021).
systemic inflammatory response syndrome (12 papers, 1995 to 2025). SIRS is a serious condition related to systemic inflammation, organ dysfunction, and organ failure. "CRS is an acute systemic inflammatory response syndrome caused by the release of inflammatory cytokines such as Interleukin-2 (IL-2), IL-2 receptor a, IL-6, IL-8, IL-10, interferon-γ, and tumor necrosis factor." (PMID 38098580, 2023). "Additional pro-inflammatory cytokines associated with sepsis syndromes were influenced by saeR/S as serum IL-6 and IL-2 concentrations were significantly lower in MW2ΔsaeR/S-infected mice (P<0.01)." (PMID 21603642, 2011). "Additionally, high-dose IL-2 therapy was associated with serious adverse events, including hypotension secondary to capillary leak syndrome and systemic inflammatory response syndrome (SIRS)-like symptoms." (PMID 40647561, 2025). "Commonest toxicity associated with HD IL-2 is hypotension, secondary to underlying capillary leak, reduced peripheral vascular resistance and increased cardiac output similar to a systemic inflammatory response syndrome (SIRS) syndrome that reflects the mechanism of action of IL-2." (PMID 28923120, 2017). "Toxicity associated with high-dose recombinant interleukin 2 (rIL-2) therapy simulates a sepsis syndrome, but the mechanism remains unclear." (PMID 7669573, 1995). "Massive release of IL-2, IL-6, and TNF-α underlies the systemic inflammatory response syndrome (SIRS)." (PMID 41010851, 2025). "This immune-mediated injury, accompanied by elevated concentrations of IL-1, IL-2, IL-10, and IFNγ, would lead to systemic inflammatory response syndrome (SIRS)." (PMID 35464491, 2022). "This is the most common and important toxicity of HD IL-2 treatment (70% of patients in early studies), reflecting capillary leak, decreased peripheral vascular resistance with high cardiac output, characteristic of systemic inflammatory response syndrome (SIRS)." (PMID 31546315, 2014).